RNU6-35P (RNA, U6 small nuclear 35, pseudogene)
Synonyms: RNU6-35
Gene: Small nuclear RNA gene on chromosome 4 (109,992,325 to 109,992,431, forward strand). Ensembl gene ENSG00000207260.
Homologues: Orthologues: rat U6 (89% identical). Paralogues in human: RNU6-25P (97% identical), RNU6-1 (96% identical), RNU6-2 (96% identical), RNU6-20P (96% identical), RNU6-3P (96% identical), RNU6-4P (96% identical), RNU6-5P (96% identical), RNU6-6P (96% identical), RNU6-9 (96% identical), RNU6-12P (95% identical), RNU6-1316P (95% identical), RNU6-13P (95% identical), and 1286 more.